LRFN4 (leucine rich repeat and fibronectin type III domain containing 4)
Diseases named in the same sentence as LRFN4 in open-access papers:
LRFN4 is named in the same sentence as 38 diseases in open-access papers, as found by Europe PMC text mining. Sharing a sentence is not in itself a finding about the gene and the disease. The quoted sentences say what the papers report.
gastric cancer (6 papers, 2019 to 2025). A primary or metastatic malignant neoplasm involving the stomach. "Validation through fluorescence multiplex immunohistochemistry confirmed that the association of LRFN4 protein expression with the clinicopathological features and the immune microenvironment of gastric cancer." (PMID 40386777, 2025). "Our data support the potential of key genes, especially LRFN4, as diagnostic and prognostic biomarkers of gastric cancer." (PMID 34686626, 2021). "Flow cytometry analysis indicated that LRFN4 inhibited apoptosis in gastric cancer cell lines while enhancing cell cycle arrest in the S phase." (PMID 40386777, 2025). "High LRFN4 expression correlated with poor prognosis in gastric cancer (FP, P = 0.0011; PPS, P = 0.00018), ovarian cancer (RFS, P = 0.045), colon cancer (relapse-free survival, P = 0.0019), and lung cancer (P = 0.00026)." (PMID 40386777, 2025). "In the present work, comprehensive survival analysis and Cox regression analysis found that upregulation of DPT and LRFN4 correlated with good prognosis in gastric cancer patients." (PMID 34686626, 2021). "Patients with high expression of LRFN4 had a higher survival rate than a low-expression group, and thus the potential protective role of LRFN4 in gastric cancer should be further explored." (PMID 34686626, 2021). "The correlation with immune cell markers, especially macrophage infiltration, indicates that LRFN4 could play a role in the local immune response in gastric cancer." (PMID 40386777, 2025). "This suggests that LRFN4 may enhance the survival of gastric cancer cells by inhibiting apoptosis and may play a role in regulating the cell cycle, particularly during the S phase." (PMID 40386777, 2025). "LRFN4 is upregulated in clinical gastric cancer cells and fibroblasts, and a high level of LRFN4 is found to be substantially linked with tumor invasive features and shorter survival rate of patients, and LRFN4 overexpression is associated with higher risk of gastric cancer." (PMID 40070576, 2025). "Overexpression of LRFN4 and LOC100506388 was associated with a higher risk of gastric cancer." (PMID 34686626, 2021). "FAM107A (Family With Sequence Similarity 107 Member A) with ADAM12, CEP55, LRFN4, INHBA, ADH1B, DPT, and LOC100506388 were analyzed and evaluated as potential prognostic genes for gastric cancer." (PMID 38609844, 2024). "Among these genes, LRFN4, DPT, and LOC100506388 were identified as having a potential prognostic role in gastric cancer, as determined through a nomogram." (PMID 38609844, 2024). "Compared with normal tissues, ADAM12, CEP55, LRFN4, and INHBA were up-regulated in gastric cancer samples, while ADH1B, DPT, FAM107A, and LOC100506388 were downregulated." (PMID 34686626, 2021). "LRFN4, DPT, and LOC100506388 were identified as potential prognostic genes for gastric cancer through a nomogram." (PMID 34686626, 2021).
leukemia (5 papers, 2019 to 2025). A malignant (clonal) hematologic disorder, involving hematopoietic stem cells and characterized by the presence of primitive or atypical myeloid or lymphoid cells in the bone marrow and the blood. "Numerous studies have investigated LRFN4, establishing a functional connection between LRFN4 and the development of tumors, including in colon cancer, lung cancer, and leukemia." (PMID 40386777, 2025). "The protein “leucine rich repeat and fibronectin type III domain containing 4” (LRFN4) is expressed in a variety of cancers and leukemia cells." (PMID 34686626, 2021). "LRFN4 is expressed in various tumors and leukemia cell lines." (PMID 40070576, 2025). "Recently, LRFN4 has been found to be expressed in a variety of tumors and leukemia cell lines." (PMID 40070576, 2025). "In leukemia, LRFN4 might contribute to tumorigenesis by disrupting the normal regulation of hematopoiesis." (PMID 40386777, 2025). "LRFN4, also known as SALM3, was expressed in many tumors and leukemia cell lines." (PMID 36699465, 2022). "In addition, they also showed that SALM3/LRFN4 was expressed in a variety of human leukemia and cancer cell lines, such as Jurkat, MKN45, SW480, and PANC-1." (PMID 31089399, 2019).
breast carcinoma (3 papers, 2024 to 2025). "Previous reports on lung, colon, and breast cancers have demonstrated that LRFN4’s ability to enhance cell proliferation, invasion, and chemotherapy resistance, suggesting its involvement in multiple oncogenic pathways." (PMID 40386777, 2025). "Using the Kaplan-Meier plotter tool, high LRFN4 expression was associated with poor OS (P = 0.017), distant metastasis-free survival (DMFS, P = 0.019), and recurrence-free survival (RFS, P = 0.049) in breast cancer, and with progression-free interval (PFI) in various other cancer types." (PMID 40386777, 2025). "The role of LRFN4, BATF2, and HGSNAT in breast cancer remains unexplored." (PMID 39720180, 2024).
stomach adenocarcinoma (3 papers, 2021 to 2025). "LRFN4 is a risk gene for ovarian cancer and a prognostic biomarker for stomach adenocarcinoma." (PMID 40070576, 2025). "In addition, LRFN4 is a risk gene for ovarian cancer and a prognostic biomarker for stomach adenocarcinoma." (PMID 40070576, 2025). "The use of fluorescence-based mIHC technology in stomach adenocarcinoma (STAD) tissues to study LRFN4 protein expression and its correlation with clinical characteristics validates the bioinformatics findings at the protein level." (PMID 40386777, 2025). "Domain-specific changes, such as Q48*p of the fn3 domain, were detected in isolated cases of lung adenocarcinoma (LUAD) and stomach adenocarcinoma (STAD), potentially leading to missense mutations in the LRFN4 gene, highlighting the diverse genetic landscapes associated with LRFN4 alterations." (PMID 40386777, 2025).
bladder cancer (2 papers, 2021 to 2025). "More importantly, it was reported that PTPRD interacting with its ligand LRFN4 was related to responses to ICIs in bladder cancers but unclear in NSCLC yet." (PMID 34615542, 2021). "Consistent with our findings, a recent study reported that the interaction of PTPRD (referred to WT) with its ligand LRFN4 was related to a poor response to Atezolizumab in bladder cancer s." (PMID 34615542, 2021).
lung adenocarcinoma (2 papers, 2025). A carcinoma that arises from the lung and is characterized by the presence of malignant glandular epithelial cells. "This study aims to explore the effect of LRFN4 in lung adenocarcinoma (LUAD)." (PMID 40070576, 2025).
adrenocortical carcinoma (1 paper, 2025). "Notably, LRFN4 expression was markedly reduced in TGCT, thyroid carcinoma (THCA), and adrenocortical carcinoma (ACC) tumor tissues." (PMID 40386777, 2025).
colon cancer (1 paper, 2025). "For example, in colon cancer, LRFN4 has been shown to promote cell proliferation through regulating specific signaling pathways." (PMID 40386777, 2025).
colorectal cancer (1 paper, 2025). A primary or metastatic malignant neoplasm that affects the colon or rectum. "In colorectal cancer, high LRFN4 expression is associated with favorable OS, while in ACC, CESC, LUAD, and LIHC, it predicts a poor prognosis." (PMID 40386777, 2025).
diffuse large B-cell lymphoma (1 paper, 2025). "This analysis revealed significant differences in LRFN4 expression for diffuse large B-cell lymphoma (DLBC), glioblastoma (GBM), lower-grade glioma (LGG), skin cutaneous melanoma (SKCM), testicular germ cell tumors (TGCT), and thymoma (THYM)." (PMID 40386777, 2025).
epilepsy (1 paper, 2018). A brain disorder characterized by episodes of abnormally increased neuronal discharge resulting in transient episodes of sensory or motor neurological dysfunction, or psychic dysfunction. "This study showed that SALM3/Lrfn4 expression is significantly increased in two distinct animal models of epilepsy, and further found that suppression of SALM3 expression by virus-mediated SALM3 knockdown ameliorates seizure activity as well as neuronal hyperexcitability." (PMID 29674953, 2018).
prostate adenocarcinoma (1 paper, 2025). "Prostate adenocarcinoma (PRAD): LRFN4 was associated with T cells, CD8+ T cells, cytotoxic lymphocytes, B lineage cells, NK cells, myeloid dendritic cells, neutrophils, endothelial cells, and fibroblasts." (PMID 40386777, 2025).
rectum adenocarcinoma (1 paper, 2025). An adenocarcinoma arising from the rectum. "Despite the unavailability of certain data, such as rectum adenocarcinoma (READ) on the cBioPortal platform, the prevalence of LRFN4 alterations in digestive system malignancies was evaluated, showing an overall incidence of 3%." (PMID 40386777, 2025).
cancer (6 papers, 2019 to 2025). A tumor composed of atypical neoplastic, often pleomorphic cells that invade other tissues. "Significantly, LRFN4 expression was associated with immune subtypes, indicating its potential role in regulating immune responses in cancers." (PMID 40386777, 2025). "Each cancer type possesses unique genetic mutations, epigenetic modifications, and microenvironmental factors that can influence the function of LRFN4." (PMID 40386777, 2025). "To explore the clinical relevance, we examined the association between LRFN4 alterations and survival outcomes across various cancers." (PMID 40386777, 2025). "Given the observed pan-cancer overexpression of LRFN4, its association with cancer progression was further elucidated by assessing its correlation with pathological staging." (PMID 40386777, 2025). "This study presents a comprehensive summary of current evidence derived from cellular and animal experiments, highlighting the association between LRFN4 and different types of cancer." (PMID 40386777, 2025). "The expression profiles of LRFN4 across multiple cancer types were analyzed using data from The Cancer Genome Atlas (TCGA)." (PMID 40386777, 2025). "Overall, these results highlight LRFN4’s potential as a key regulator in tumor pathogenesis and its value in cancer prognosis and therapy." (PMID 40386777, 2025). "It is likely that LRFN4 interacts differentially with the TME or cellular machinery depending on the cancer type, ultimately influencing patient outcomes in various ways." (PMID 40386777, 2025). "This study represents the first comprehensive pan-cancer analysis of LRFN4, aiming to systematically characterize its expression pattern and prognostic significance." (PMID 40386777, 2025). "This study represents the first pan-cancer analysis of LRFN4 utilizing data from the TCGA project and the GEO database." (PMID 40386777, 2025). "The expression of LRFN4 protein in cancer tissues is higher than in paracancerous tissues and benign gastric disease tissues." (PMID 34686626, 2021). "The enhanced apoptosis following LRFN4 knockdown suggests that LRFN4 might act as an oncogene by inhibiting apoptotic pathways, thereby promoting cancer cell survival." (PMID 40386777, 2025). "Because of the unknown relationship between LRFN4 and cancer, the correlations between LRFN4 and cancer need to be verified." (PMID 34512711, 2021). "This could lead to overestimation or underestimation of LRFN4’s roles in different cancer types." (PMID 40386777, 2025). "Therefore, the specific effects of LRFN4 on GC and other cancers need further studies." (PMID 32908454, 2020). "The observed correlations between LRFN4 expression and both TMB, as well as MSI, in certain cancers suggest that LRFN4 can influence the immunogenicity of tumors." (PMID 40386777, 2025). "LRFN4, ADAMTS12, MCEMP1, HP and MUC15 are all cancer-related biomarkers, and all of them can also be used in judgment of cancer incidence in an independent manner." (PMID 32908454, 2020). "Nevertheless, a recent study reported that SALM3, also known as LRFN4, is expressed in some cancer cell lines, such as Panc-1, JURKAT-1, and MKN7." (PMID 31089399, 2019). "However, the variable correlation between LRFN4 expression and overall survival (OS) and disease-free survival (DFS) across different cancer types underscores its complex prognostic value." (PMID 40386777, 2025).
tumor (5 papers, 2019 to 2025). "Furthermore, LRFN4 protein expression exhibited significant associations with vascular invasion, tumor size, and TNM stage." (PMID 40386777, 2025). "Moreover, LRFN4 expression was associated with the presence of tumor-infiltrating immune cells, particularly in gastrointestinal tumors, reflecting immune cell genetic signatures." (PMID 40386777, 2025). "Zheng and colleagues have documented that in colorectal cancer (CRC), LRFN4 expression was tightly correlated with tumor location and TNM staging." (PMID 40070576, 2025). "This investigation focused on the relationship between LRFN4 expression and tumor immunity, specifically through infiltration correlation analysis." (PMID 40386777, 2025). "Future studies should include a more diverse patient cohort and sample types, as such diversification can provide valuable insights and facilitate the investigation of the molecular drivers of LRFN4 in tumor occurrence." (PMID 40386777, 2025). "Future investigation should focus on the role of LRFN4 within the tumor immune microenvironment and its involvement in tumor responses to immunotherapy." (PMID 40386777, 2025). "Tumor heterogeneity can lead to variations in LRFN4 expression within a single tumor, making it difficult to accurately assess its prognostic value." (PMID 40386777, 2025). "Although the receiver operating characteristic (ROC) analysis supports the potential of LRFN4 as a prognostic biomarker, its predictive ability is confounded by factors such as tumor heterogeneity, immune infiltration, and genetic alterations." (PMID 40386777, 2025). "Using TCGA cohort data, we analyzed the genetic alteration status of LRFN4 across multiple tumor types." (PMID 40386777, 2025). "Except for CESC, KIPAN, and LUSC where negative correlations were observed, most immune-related genes positively correlated with LRFN4 expression across tumor types (P < 0.05)." (PMID 40386777, 2025). "This study investigated the potential role of human LRFN4 in tumor development and progression by referencing its mRNA (NM_001363524.2) and protein (NP_001350453.1) sequences." (PMID 40386777, 2025). "In a previous study, the expression level of LRFN4 was high in tumor cells, which was consistent with present results." (PMID 34512711, 2021). "In other tumor types, a positive correlation with LRFN4 was found (P < 0.05)." (PMID 40386777, 2025). "It is postulated that the LRFN4 protein could serve as a potential biomarker for screening multiple tumors and likely plays a critical role in tumor initiation and progression." (PMID 40386777, 2025). "The specific correlation between LRFN4 expression and the expression of immunosuppressive checkpoint proteins (ICPs) in most tumor types, especially in LIHC, OV, and THCA, indicates that LRFN4 may be involved in immune evasion mechanisms." (PMID 40386777, 2025). "Immune infiltration can modulate the tumor microenvironment, and LRFN4 may interact with immune cells in a context-dependent manner." (PMID 40386777, 2025). "In addition, in CRC, LRFN4 expression was closely correlated with tumor location, T staging, N staging and TNM staging, these findings were consistent with our results." (PMID 40070576, 2025). "Given the crucial role of immune cells in tumor biology, LRFN4 may profoundly influence the function and behavior of tumor-associated macrophages (TAMs) and other immune cells." (PMID 40386777, 2025). "This interaction could involve LRFN4 - mediated regulation of immune cell activation or tumor cell evasion mechanisms." (PMID 40386777, 2025). "Data from the TCGA, CCLE platforms, and GEO databases were utilized, along with molecular characteristics such as gene expression, genetic alterations, DNA methylation, and protein phosphorylation, to conduct an in-depth examination of the LRFN4 gene across 33 distinct tumor types." (PMID 40386777, 2025).
tumor (continued). "As a member of the leucine - rich repeat and fibronectin type III domain-containing family and a type I transmembrane glycoprotein, LRFN4 may interact with diverse cellular components within the tumor microenvironment (TME)." (PMID 40386777, 2025). "This indicates that LRFN4 may promote T cell exhaustion by upregulating PD-1 expression, thereby inhibiting anti-tumor immune responses." (PMID 40070576, 2025). "For instance, LRFN4 might interact with chemokine receptors on immune cells, guiding their movement towards the tumor site." (PMID 40386777, 2025). "LRFN4 expression was strongly correlated with clinical prognosis, immune subtypes, molecular subtypes, immune checkpoint (ICP) genes, tumor mutational burden (TMB), microsatellite instability (MSI), and immune infiltration, which were measured by ESTIMATE scores." (PMID 40386777, 2025). "It is hypothesized that LRFN4 promotes the conversion of TAMs into immunosuppressive M2 - type macrophages, which secrete cytokines such as interleukin-10 and transforming growth factor-β that inhibit anti-tumor immune responses." (PMID 40386777, 2025). "While this study elucidates the expression of LRFN4 in LUAD and its implications for prognosis, tumor microenvironment, and drug sensitivity, several limitations warrant attention." (PMID 40070576, 2025). "It has also been demonstrated that NRCAM, LRFN4, and PHGDH are upregulated in CRC tissues compared to normal samples around the tumor and serve as predictors of poor clinical outcomes in advanced CRC patients 42-44." (PMID 38706895, 2024). "In liver hepatocellular carcinoma (LIHC), the positive correlation between LRFN4 and immunotherapy targets such as PDCD1 and CTLA4 implies that LRFN4 can impact the interaction between immune cells and tumor cells, potentially modulating the efficacy of immune checkpoint blockade (ICB) therapy." (PMID 40386777, 2025). "Co-expression analyses of LRFN4 and ICP genes were performed across 33 tumor types." (PMID 40386777, 2025). "From TCGA tumor expression data via GEPIA2, the top 100 genes positively correlated with LRFN4 expression were determined, among which TPX2 (R = 0.36), KIF18B (R = 0.39), RCE1 (R = 0.53), PCNXL3 (R = 0.49), and SAMD1 (R = 0.48) showed significant correlations (P < 0.001)." (PMID 40386777, 2025). "Notably, the correlation between LRFN4 expression levels and clinical features in COAD and PAAD was found to be weaker, as these tumor types exhibited fewer CNVs." (PMID 40386777, 2025). "For instance, LRFN4-mediated interactions could lead to changes the secretion of cytokines and growth factors in the TME, altering the availability of nutrients and oxygen for both tumor and immune cells." (PMID 40386777, 2025). "Positive or negative correlations of LRFN4 with TMB and MSI imply that LRFN4 may either enhance or suppress the generation of tumor neoantigens or affect DNA repair processes." (PMID 40386777, 2025).
LRFN4 also shares sentences with these, for which no sentence is quoted: ovarian carcinoma (2 papers); Burkitt lymphoma (1); cholangiocarcinoma (1); colorectal adenocarcinoma (1); digestive system cancer (1); esophageal cancer (1); gastrointestinal tumors (1); glioblastoma (1); head and neck squamous cell carcinoma (1); hepatocellular carcinoma (1); infection (1); liver cancer (1); lung carcinoma (1); lung squamous cell carcinoma (1); lymph node metastasis (1); monocytic leukemia (1); skin cutaneous melanoma (1); status epilepticus (1); T-cell leukemia (1); testicular germ cell tumor (1); thymoma (1); thyroid carcinoma (1); uterine corpus endometrial carcinoma (1).